SPATA45 (spermatogenesis associated 45)
Synonyms: C1orf227; LOC149643
Tractability: No criterion of Open Targets' tractability assessment is met for any kind of drug.
Gene: Protein-coding gene on chromosome 1 (212,830,141 to 212,847,649, reverse strand). Ensembl gene ENSG00000185523.
Subcellular location (Human Protein Atlas): Cytosol; Nuclear speckles
Genetic constraint (gnomAD): Loss-of-function variants: 2 observed, 5.53 expected, observed/expected ratio (o/e) 0.36, 90% interval 0.15 to 1.13. That is too few expected variants to judge how well the gene tolerates losing a copy. Missense variants: 105 observed, 110.89 expected, observed/expected ratio (o/e) 0.95, 90% interval 0.81 to 1.11. Synonymous variants: 39 observed, 38.63 expected, observed/expected ratio (o/e) 1.01, 90% interval 0.78 to 1.32.
Homologues: Orthologues: macaque SPATA45 (92% identical), pig SPATA45 (69% identical), guinea pig SPATA45 (68% identical), rabbit SPATA45 (68% identical), rat SPATA45 (62% identical), mouse Spata45 (58% identical), zebrafish spata45 (27% identical).
Diseases named in the same sentence as SPATA45 in open-access papers:
SPATA45 is named in the same sentence as 1 disease in open-access papers, as found by Europe PMC text mining. Sharing a sentence is not in itself a finding about the gene and the disease.
SPATA45 shares sentences with these, for which no sentence is quoted: psoriasis (1 paper).